FAP (fibroblast activation protein alpha)
Diseases named in the same sentence as FAP in open-access papers (continued):
Sharing a sentence is not in itself a finding about the gene and the disease.
invasive breast carcinoma (5 papers, 2018 to 2024). A carcinoma that infiltrates the breast parenchyma. "In invasive breast cancer, a comprehensive IHC analysis approach recently identified four functional different fibroblast subsets, of which one subset was high in fibroblast activation protein (FAP) and PDGFRb expression and functionally linked to immunosuppression and pro-invasive effects." (PMID 33661437, 2021). "The right panel suggested that the patients with higher expression of FAP-a may have the higher possibility of progression to invasive breast cancer." (PMID 31921678, 2019). "The study demonstrated that the overexpression of FAP-a in stromal fibroblasts and GOLPH3 in carcinoma cells are highly predictive of DCIS recurrence and progression into invasive breast cancer." (PMID 31921678, 2019). "To this end, we specifically examined the correlation between FAP-a and GOLPH3 expression, their clinico-pathological values in predicting the recurrence or progression of DCIS into invasive breast cancer." (PMID 31921678, 2019). "We have shown here that the presence of FAP-a in stromal fibroblasts and GOLPH3 in carcinoma cells are reliable biomarker of DCIS recurrence and progression into invasive breast cancer." (PMID 31921678, 2019). "The combination of FAP-a and GOLPH3 in predicating the recurrence or progression of DCIS into invasive breast cancer was specifically examined." (PMID 31921678, 2019). "FAP-a and GOLPH3 serve as novel markers in predicting the recurrence or progression of DCIS into invasive breast cancer." (PMID 31921678, 2019). "The present study aimed to retrospectively evaluate the pathological value of FAP-a and GOLPH3 in predicting the recurrence or progression of DCIS to invasive breast cancer." (PMID 31921678, 2019). "Thus, we identified that FAP-a and GOLPH3 might potentiate as a reliable biomarker for predicting the DCIS recurrence and progression of DCIS into invasive breast cancer." (PMID 31921678, 2019). "Among 132 FAP-a positive DCIS patients, 41 recurred to DCIS, 52 recurred, and progressed into invasive breast cancer, while the remaining 39 cases experienced no recurrence." (PMID 31921678, 2019).
Pleural effusion (5 papers, 2012 to 2025). The presence of an excessive amount of fluid in the pleural cavity. "is designed to test the safety of FAP-specific re-directed T cells after injection in the pleural effusion, we developed an intra-peritoneal model for the adoptive transfer of T cells to model the function of these cells in a body cavity." (PMID 23937772, 2013). "Since this trial is the first trial evaluating FAP-specific re-directed T cells in the pleural effusion, all enrolled patients will be treated with the lowest suggested number of cells and monitored for the first 48h at an intermediate care unit." (PMID 23259649, 2012). "FAP-specific T cells will be directly injected in the pleural effusion of patients with MPM." (PMID 23259649, 2012). "First, to confirm that the cells with spindle shape obtained from the carcinomatous pleural effusion were fibroblasts, we investigated the mRNA expression of α‐SMA and FAP by qPCR." (PMID 30734495, 2019).
prostate tumor (5 papers, 2021 to 2026). "Baring this potential, FAP might also play a role in more advanced de-differentiated tumors of the prostate, such as those with neuroendocrine signatures and loss of PSMA expression." (PMID 34854061, 2022). "Our findings reinforce the biological and clinical relevance of stromal FAP in the prostate tumour microenvironment." (PMID 41410015, 2026). "Recent studies and case reports, however, postulate FAP-positive PET/CT in PSMA negative/FDG positive disease, underlining the relevance of FAP-based imaging only in late stages and clinical aggressive tumors of the prostate." (PMID 34854061, 2022). "Patient A3 and A4 had no expression of FAP in prostate tumor nor LN." (PMID 34854061, 2022).
rectal cancer (5 papers, 2015 to 2024). A primary or metastatic malignant neoplasm that affects the rectum. "The association is controversial in rectal cancer and patients with high CIMP and FAP expression at the tumour front." (PMID 38397199, 2024). "FAPα is also involved in tumor re-growth and recurrence and high FAPα expression is correlated with poor prognosis in rectal cancer following chemoradiotherapy." (PMID 25593080, 2015). "In rectal cancer FAP expression in CAFs correlates with poor prognosis after chemoradiotherapy." (PMID 34854061, 2022). "FAP expression in CRCs is correlated with cancers of the rectum, however no other clinical or molecular characteristics were found to correlate with FAP expression." (PMID 39335130, 2024).
serous ovarian cancer (5 papers, 2019 to 2024). "Here, we used immunohistochemical (IHC) staining and 7-color multiplex staining to evaluate CD8 (cluster of differentiation 8), CD68, PD-L1 (programmed death-ligand 1), CD34, FAP (fibroblast activation protein), and cytokeratin in 220 tissue cores from 26 high-grade serous ovarian cancer samples." (PMID 31772388, 2019). "In high-grade serous ovarian cancer, the CD49e+ CAF population was divided into two subgroups, FAP-high and FAP-low group." (PMID 36185262, 2022).
stomach adenocarcinoma (5 papers, 2022 to 2024). "In mouse models of stomach adenocarcinoma (STAD), FAP-positive CAFs significantly contribute to cell proliferation and exhibit reduced sensitivity to anti-PD1 therapy." (PMID 37490719, 2023). "We also investigated the impact of CAF markers highly clustered with COL1A1 and COL5A1 in correlation analysis, namely THBS2, FAP, INHBA, S100A4, COL11A1, or MMP11, on the outcome of CAF infiltration in stomach adenocarcinoma." (PMID 35739492, 2022). "To further explore the characteristics of FAP expression in various clinical features and biological functions, we concentrated on the ACRG cohort of 300 stomach adenocarcinoma samples, which contains extensive clinical information." (PMID 35359436, 2022).
adenoid cystic carcinoma (4 papers, 2021 to 2022). A malignant tumor arising from the epithelial cells. "Fibroblast Activation Protein (FAP) is a new target for positron emission tomography and computed tomography (PET/CT) imaging of epithelial tumours, such as adenoid cystic carcinomas (ACCs)." (PMID 36077788, 2022). "However, in a series of 12 patients with adenoid cystic carcinomas, a strong FAPI uptake was established within all patients that correlated with FAP overexpression in the tumor." (PMID 34638433, 2021).
bladder tumor (4 papers, 2019 to 2025). "Here we observed that HLA-I loss in bladder tumors is associated with T cell exclusion and tumor encapsulation with stromal elements rich in FAP-positive cells." (PMID 34298868, 2021). "Based on the frequency and tissue distribution of FAP+ fibroblasts, we classified bladder tumors into two groups: non-encapsulated tumors with diffuse distribution of scarce FAP+ fibroblasts and encapsulated tumors with the stroma rich in FAP+ fibroblasts." (PMID 34298868, 2021).
cardiomyopathy (4 papers, 2020 to 2025). A disease of the heart muscle or myocardium proper. "Potential applications of FAP can include the identification of early fibrosis in cardiomyopathy, the assessment of therapeutic responses and the prediction of cardiac dysfunction." (PMID 40278373, 2025).
cervical squamous cell carcinoma (4 papers, 2023 to 2025). A squamous cell carcinoma arising from the cervical epithelium. "Increased FAP expression was associated with poor prognosis in cancers such as Adrenocortical carcinoma (ACC), BLCA, Cervical squamous cell carcinoma and endocervical adenocarcinoma (CESC), HNSC, KIRC, KIRP, Brain Lower Grade Glioma (LGG), and STAD." (PMID 39055892, 2024).
colitis (4 papers, 2022 to 2024). Inflammation of the colon. "TWIST1 deletion in vivo was also associated with a reduction in FAP expression in fibroblasts isolated from the colon of Twist1Δ/ΔCol1a2 mice compared with their littermates after DSS-induced colitis." (PMID 39042469, 2024). "Single-cell transcriptomic profiling of chronic dextran sulfate sodium salt murine colitis model revealed that CD81+Pi16– fibroblasts exhibited transcriptomic and functional similarities to human FAP+ fibroblasts." (PMID 39024569, 2024).
COVID-19 (4 papers, 2021 to 2025). A disease caused by infection with severe acute respiratory syndrome coronavirus 2. "In this study we aimed to explore pulmonary and muscle fibroblast activation protein (FAP) activity in former critical COVID-19 patients with persistent dyspnea, using [68Ga]FAPI-46 PET/CT." (PMID 40542858, 2025). "We explored the expression of FAP using [68Ga]FAPI-46 PET/CT in PASC patients after critical COVID-19." (PMID 40542858, 2025). "Pulmonary FAP expression, representing fibroblast activation, was first described in a former COVID-19 patient showing pulmonary [68Ga]FAPI uptake matching ground glass opacities on HRCT." (PMID 40542858, 2025). "Our aim was to explore pulmonary FAP activity in former critical COVID-19 patients, with persistent complaints of dyspnea." (PMID 40542858, 2025). "The proteins COL10A1/FAP/FN1 were found to be common signature genes for COVID-19 and PC, were significantly up-regulated in both diseases and showed good diagnostic efficacy for PC." (PMID 38063927, 2023). "The clustering typing based on the expression levels of COL10A1/FAP/FN1 of COVID-19 signature genes provides a new typing approach for PC, enabling a more refined analysis of PC and providing a good reference for the sophisticated treatment of PC and further clinical studies." (PMID 38063927, 2023). "Then, COL10A1/FAP/FN1 were defined as the common signature genes of COVID-19 and PC in this study." (PMID 38063927, 2023). "The upregulated expression of COL10A1/FAP/FN1, the characteristic genes of COVID-19, are potential diagnostic targets for PC, and the upregulated expression of FN1 may promote the progression of PC by activating the PI3K-AKT signaling pathway." (PMID 38063927, 2023). "Within the COVID-19 positive pandemic group, IBS was identified in 21 cases (91.3%) and AM in two cases (8.7%), while within the COVID-19 negative pandemic group, IBS cases were present in only six cases (54.5%), followed by FD and AM with two cases (18.2%) and FAP-NOS in one case (9.1%)." (PMID 35455000, 2022).
endometrial cancer (4 papers, 2015 to 2024). Primary or metastatic malignant neoplasm involving the endometrium (mucous membrane that lines the endometrial cavity). "IF staining for α-SMA and FAP demonstrated that fibroblasts derived from endometrial cancer samples were activated." (PMID 38459564, 2024). "FAP expression was detected rarely in some cancer cells, such as differentiated carcinomas and endometrial carcinoma." (PMID 25775399, 2015). "CAFs isolated from endometrial cancer tissues were highly positive for α-SMA, FSP1, and FAP expression and moderately positive for vimentin expression, and were found to play diverse roles in endometrial tumor progression." (PMID 33808627, 2021). "CAF markers that have been identified in endometrial cancer include α-SMA, FSP1, FAP, and vimentin." (PMID 33808627, 2021).
endometriosis (4 papers, 2024 to 2025). The growth of functional endometrial tissue in anatomic sites outside the uterine body. "To determine whether FAP positivity occurs only among the endometriosis-associated CD10-positive cytogenic stroma, we conducted an immunohistochemical double staining for FAP and CD10." (PMID 39959762, 2025). "Do activated fibroblasts expressing fibroblast activation protein-α (FAP) – which is traceable in positron emission topography/computed topography (PET/CT) – play a role in the microenvironment of endometriosis?" (PMID 39959762, 2025). "This study proves the presence of FAP-positive fibroblasts in endometriosis by immunohistological methods." (PMID 39959762, 2025). "In an effort to elucidate the involvement of FAP in endometriosis, the authors examined 245 tissue specimens obtained from 159 patients, encompassing lesions from multiple anatomical locations." (PMID 41515390, 2025). "Our results show the presence of activated FAP-expressing fibroblasts in the microenvironment of endometriosis." (PMID 39959762, 2025). "Critically for endometriosis, FAP upregulation is also initiated by benign conditions such as inflammation, hormonal influence, and wound healing." (PMID 41515390, 2025). "Our observation is supported by a recent preclinical study that found FAP expression in the immune microenvironment of endometriosis from various locations." (PMID 40183952, 2025). "In our omics results, we observed an elevation in the expression of critical fibrosis-associated proteins, including TGFBR1, α-SMA, CTHRC1, FAP, FN1, and 15 collagen proteins, in endometriosis." (PMID 38735939, 2024). "Moreover, we show that FAP expression is intertwined with the immune cell infiltrate in the microenvironment of endometriosis." (PMID 39959762, 2025). "However, to translate targeting FAP into endometriosis diagnostics, these results have to be compared to imaging data and FAP inhibitor (FAPi) PET/CT has to be validated in a structured way on a large patient cohort." (PMID 39959762, 2025). "Elevated FAP expression (H-score ≥10) was detectable in 84% of endometriosis cases in endometriomas of the ovary, superficial peritoneal lesions, deep infiltrating endometriosis, and extra-abdominal lesions and only 4% of extralesional controls." (PMID 39959762, 2025). "This case may provide a rationale for future studies systematically analyzing FAP expression in endometriosis across larger patient cohorts, investigating the value of 68Ga-FAPI PET/CT." (PMID 40183952, 2025). "Furthermore, lesions rich in FAP-positive fibroblasts exhibited higher numbers of infiltrating immune cells, notably macrophages and CD8+ T lymphocytes, highlighting potential crosstalk between stromal activation and immune responses in endometriosis pathophysiology." (PMID 41515390, 2025).
malignant fibrous histiocytoma (4 papers, 2009 to 2023). "All desmoid fibromatosis, myxofibrosarcoma, solitary fibrous tumor, and undifferentiated pleomorphic sarcoma samples had medium or high FAP overall scores." (PMID 37333052, 2023).
malignant glioma (4 papers, 2010 to 2023). A grade III or grade IV glioma arising from the central nervous system. "A series of FAP tests were conducted on 33 cases of malignant gliomas in order to ascertain their efficacy in monitoring the progression of the disease in relation to imaging observations." (PMID 37864148, 2023). "We next assessed FAP protein expression using immunohistochemistry (IHC) on FFPE specimens of malignant gliomas (13 IDH-wt GBM, 1 IDH-mutant anaplastic astrocytoma and 1 IDH-mutant GBM) collected at MGH." (PMID 33308315, 2020).
metastatic melanoma (4 papers, 2019 to 2025). A melanoma that has spread from its primary site to another anatomic site. "Since IL-2 based immunotherapy is efficient against metastatic melanomas, albeit associated with toxicity, we designed a tumor-targeting FAP-IL2v with abolished CD25 binding." (PMID 35874707, 2022). "This study explored the combination of fibroblast activation protein (FAP) IL2 variant (FAP-IL2v), a novel immune-cytokine, with pembrolizumab in patients with advanced and/or metastatic melanoma." (PMID 39895413, 2025). "In this study, we determine the clinical significance of pretreatment CAF (Thy1, SMA, FAP) profiles according to both in situ cell counts and QIF protein expression in relation to immunotherapy outcome in metastatic melanoma." (PMID 31337426, 2019).
metastatic prostate carcinoma (4 papers, 2020 to 2025). A carcinoma that arises from the prostate gland and has spread to other anatomic sites. "Corroborating this idea, the present study indicates the use of FAP-based diagnostics only in advanced metastatic prostate cancer or in case of doubtful lesions, therapy failure and suspected other primary tumors." (PMID 34854061, 2022). "However, this was due to only one patient with metastatic prostate cancer demonstrating very high FAP concentrations (baseline: 451 ng/ml; post radiation: 346 ng/ml) who received a single dose of 18 Gy and a cumulative radiation dose of 54 Gy." (PMID 40690098, 2025).
ovarian tumors (4 papers, 2016 to 2023). "As such, TGFβ-secreting myCAF is very abundant in immune-excluded ovarian tumors, and αSMA+FAP+ CAFs from head and neck tumors have been shown to inhibit CD8+ T cell proliferation and to promote the recruitment of Tregs in a TGFβ-dependent manner." (PMID 36338519, 2022). "To examine whether fibroblast activation in ovarian tumors is related to lower tumor-infiltrating lymphocyte counts in tumor parenchyma, we evaluated two different fibroblast activation markers, FAP and α-SMA." (PMID 32587587, 2020). "Transcript levels of ACTA2 (the gene encoding αSMA) and FAP were significantly higher in SPHK1-High tumors than in SPHK1-Low tumors in both the AOCS and TCGA datasets, suggesting that SPHK1 could be associated with an increased abundance of CAFs in ovarian tumors." (PMID 26716409, 2016). "For example, based on an integrated flow cytometry analysis of FAP, CD29, αSMA, FSP1, PDGFRβ, and CAV1 expression, four different CAFs subsets (named CAF-S1 to -S4) have been identified in different breast and ovarian tumor subtypes and differentially accumulate within the TME." (PMID 36338519, 2022).
renal carcinoma (4 papers, 2016 to 2020). A carcinoma arising from the epithelium of the renal parenchyma or the renal pelvis. "Nevertheless, there was a positive correlation between FAP expression in both locations, reminiscent of our previous findings in renal cancer." (PMID 32428869, 2020). "For a better understanding of the prognostic implications of this serine peptidase in renal cancer, we analyzed the immunohistochemical expression of FAP in CAFs both in primary tumors and in their metastases from a series of CCRCC." (PMID 28033421, 2016). "The study of FAP in renal cancer was an unexplored territory until recent years." (PMID 33207686, 2020). "In this study, the immunostaining of FAPp and FAPm was positive in 100% of sarcomatoid CCRCCs, a finding that supports the idea that FAP and CAFs could also confer aggressive behavior to renal cancer cells by regulating EMT." (PMID 28033421, 2016). "The CAFs-containing stroma without DES staining had higher FN1 and FAP staining than did the renal cancer cells." (PMID 33634098, 2020).